JAKMIP1 (janus kinase and microtubule interacting protein 1)
Description:
Associates with microtubules and may play a role in the microtubule-dependent transport of the GABA-B receptor. May play a role in JAK1 signaling and regulate microtubule cytoskeleton rearrangements.
Synonyms: GABABRBP; JAMIP1; MARLIN1; FLJ31564
Tractability: Antibody: UniProt places it where antibodies can reach, with medium confidence. PROTAC: ubiquitination databases record sites on it; its protein half-life has been measured.
Gene: Protein-coding gene on chromosome 4 (6,026,199 to 6,200,591, reverse strand). Ensembl gene ENSG00000152969.
Subcellular location: Cytoplasm, cytoskeleton; Membrane
Gene Ontology:
Molecular function: GABA receptor binding; protein binding; RNA binding; kinase binding; microtubule binding
Biological process: cognition
Cellular component: membrane; ribonucleoprotein complex; cytoskeleton
Genetic constraint (gnomAD): Loss-of-function variants: 23 observed, 83.27 expected, observed/expected ratio (o/e) 0.28, 90% interval 0.2 to 0.39. The upper end of that interval is the gene's LOEUF score, 0.39, which puts it in group 1 of 6, group 1 being the genes least tolerant of losing a copy. Missense variants: 754 observed, 966.1 expected, observed/expected ratio (o/e) 0.78, 90% interval 0.73 to 0.83. Synonymous variants: 456 observed, 422.54 expected, observed/expected ratio (o/e) 1.08, 90% interval 1 to 1.17.
Homologues: Orthologues: chimpanzee JAKMIP1 (99% identical), macaque JAKMIP1 (99% identical), dog JAKMIP1 (97% identical), pig JAKMIP1 (96% identical), guinea pig JAKMIP1 (96% identical), rat Jakmip1 (95% identical), mouse Jakmip1 (94% identical), tropical clawed frog jakmip1 (79% identical), zebrafish jakmip1 (66% identical). Paralogues in human: JAKMIP2 (66% identical), JAKMIP3 (63% identical).
Diseases named in the same sentence as JAKMIP1 in open-access papers:
JAKMIP1 is named in the same sentence as 19 diseases in open-access papers, as found by Europe PMC text mining. Sharing a sentence is not in itself a finding about the gene and the disease. The quoted sentences say what the papers report.
breast carcinoma (2 papers, 2020 to 2023). "In addition, a genomic study on DNA methylation and breast cancer risk found that methylation of JAKMIP1 was associated with breast cancer risk." (PMID 37894938, 2023). "Of the 43 differentially methylated genes associated with breast cancer risk in the individual CpG sites analysis of normal breast tissue main analysis, LHX2 was included in three DMRs, TFAP2B in two DMRs, JAKMIP1 in one DMR, and SEPT9 in one DMR." (PMID 33113958, 2020).
gastric cancer (2 papers, 2021 to 2023). A primary or metastatic malignant neoplasm involving the stomach. "Five genes, e.g., DGAT2, JAKMIP1, KRT7, PGLYRP1, and TINAGL1, showed very low correlation coefficient and/or insignificant p-values, suggesting they might not be regulated by KLF5 in human gastric cancer." (PMID 33923166, 2021).
autism spectrum disorder (1 paper, 2016). A spectrum of developmental disorders that includes autism, and Asperger syndrome. "The ninth individual carries a de novo variant in JAKMIP1, a regulator of neuronal translation that was recently found deleted in a patient with autism spectrum disorder." (PMID 27799067, 2016).
colon cancer (1 paper, 2023). "JAKMIP1 was also found to be closely associated with gene expression levels of CD8 in colon cancer." (PMID 37894938, 2023).
colorectal cancer (1 paper, 2022). A primary or metastatic malignant neoplasm that affects the colon or rectum. "In colorectal cancer, we found strong correlations between JAKMIP1 and chemokine gene expression levels." (PMID 35205408, 2022). "Moreover, the analysis of TMB differentially expressed genes (DEGs) suggested that JAKMIP1 was strongly correlated with the gene expression level of CD8+ T cell markers in colorectal cancer." (PMID 35205408, 2022). "Thus, we suggest that the TMB-related gene JAKMIP1 could enhance the immune activity of TME in colorectal cancer." (PMID 35205408, 2022).
glioma (1 paper, 2022). A benign or malignant brain and spinal cord tumor that arises from glial cells (astrocytes, oligodendrocytes, ependymal cells). "Janus kinase and microtubule-interacting protein 1; marlin-1 (JAKMIP1) was identified as being associated with IDH1 expression in the All gliomas analysis." (PMID 35877430, 2022).
HCMV infection (1 paper, 2024). "JAKMIP1, a marker of adaptive NK cells in chronic HCMV infection, was also elevated 5-fold (PFDR = 2.53 × 10–3)." (PMID 39531313, 2024).
lung carcinoma (1 paper, 2022). "In lung cancer, JAKMIP1 overexpression has been implicated in cell proliferation through activating the Wnt/β-catenin pathway." (PMID 35877430, 2022).
melanoma (1 paper, 2020). A malignant, usually aggressive tumor composed of atypical, neoplastic melanocytes. "Among them, two genes, preferentially expressed antigen in melanoma (PRAME) and Janus kinase and microtubule interacting protein 1 (JAKMIP1), were reported as cancer/testis (CT) genes that were selectively expressed in testis and cancers." (PMID 32732980, 2020).
type 2 diabetes (1 paper, 2024). "The most significant association with the GDF-15 level was a trans association with rare variants in JAKMIP1, associated with type 2 diabetes and medications used to treat it82–84." (PMID 38565889, 2024).
cancer (3 papers, 2020 to 2025). A tumor composed of atypical neoplastic, often pleomorphic cells that invade other tissues. "The JAKMIP1 gene codes for the Janus kinase and microtubule interacting protein 1 and has been shown to be highly expressed in tumor samples, where it enhances the proliferation of cancer cells." (PMID 33113958, 2020).
tumor (2 papers, 2020 to 2022). "TSPYL2, JAKMIP1, CIT, and TMTC1 were all significantly downregulated in GBM compared to non-tumor samples (p < 0.001)." (PMID 35877430, 2022).
neurodevelopmental disorder (1 paper, 2024). A behavioral and cognitive disorder with onset during the developmental period that involves impaired or aberrant development of intellectual, motor, or social functions. "The largest mediation effect size was observed for JAKMIP1 (janus kinase and microtubule interacting protein 1), a gene dysregulated in neurodevelopmental disorders which contains a maternally imprinted DMR that may impact fetal growth." (PMID 38413986, 2024).
JAKMIP1 also shares sentences with these, for which no sentence is quoted: alcoholics (1 paper); amnesia (1); autism (1); leukaemia (1); metastatic tumors (1); schizophrenia (1).